SRRD (SRR1 domain containing)
Description:
Plays a role in the regulation of heme biosynthesis and in the regulation of the expression of core clock genes.
Synonyms: SRR1L; HC/HCC
Tractability: No criterion of Open Targets' tractability assessment is met for any kind of drug.
Gene: Protein-coding gene on chromosome 22 (26,483,877 to 26,494,658, forward strand). Ensembl gene ENSG00000100104.
Subcellular location: Cytoplasm
Subcellular location (Human Protein Atlas): Cytosol
Gene Ontology:
Biological process: regulation of circadian rhythm; regulation of heme biosynthetic process
Cellular component: cytoplasm
Genetic constraint (gnomAD): Loss-of-function variants: 26 observed, 29.83 expected, observed/expected ratio (o/e) 0.87, 90% interval 0.64 to 1.21. The upper end of that interval is the gene's LOEUF score, 1.21, which puts it in group 5 of 6, group 1 being the genes least tolerant of losing a copy. Missense variants: 400 observed, 394.63 expected, observed/expected ratio (o/e) 1.01, 90% interval 0.93 to 1.1. Synonymous variants: 157 observed, 146 expected, observed/expected ratio (o/e) 1.08, 90% interval 0.94 to 1.23.
Homologues: Orthologues: chimpanzee SRRD (96% identical), macaque SRRD (91% identical), pig SRRD (77% identical), dog SRRD (72% identical), guinea pig SRRD (69% identical), rat Srrd (62% identical), rabbit SRRD (58% identical), mouse Srrd (50% identical), tropical clawed frog srrd (41% identical), zebrafish srrd (35% identical), Drosophila melanogaster CG7988 (20% identical).
Diseases named in the same sentence as SRRD in open-access papers:
SRRD is named in the same sentence as 2 diseases in open-access papers, as found by Europe PMC text mining. Sharing a sentence is not in itself a finding about the gene and the disease.
SRRD shares sentences with these, for which no sentence is quoted: infection (1 paper); virus infection (1).